IDH1 (isocitrate dehydrogenase (NADP(+)) 1)
Diseases named in the same sentence as IDH1 in open-access papers (continued):
Sharing a sentence is not in itself a finding about the gene and the disease.
tumor (continued). "Thus, the isocitrate dehydrogenase status, such as IDH-1 and IDH-2 mutations, and ATRX mutation or loss and tumours with 1p19q co-deletion has been associated with better prognosis." (PMID 32411235, 2020). "These factors included tumor grade, age of diagnosis, KPS score, and IDH1 mutation status." (PMID 33047900, 2020). "In contrast, subtype C3 contained a slightly higher proportion of cases of WHO grade II than did the other subtypes (χ2 test, FDR < 0.0001); meanwhile, the proportion of cases with mutant IDH1 in the tumor was significantly higher in subtype C3 than in subtypes C1 and C2 (χ2 test, FDR < 0.0001)." (PMID 33425739, 2020). "In addition, IDH1 mutation and low expression of ATRX and Ki67 showed marginally significant association with decreased tumor growth." (PMID 32388499, 2020). "IDH1-mutant tumors have an additional survival benefit associated with maximal resection, but in IDH1-wildtype tumors, no survival benefit is observed in association with further resection of residual tumor." (PMID 32034238, 2020). "There was a non-significant trend to increased IDH1 mutation in moderate/strong IGF-1R tumours (p = 0.12)." (PMID 31857716, 2020). "Given the importance of IDH2 in the biogenesis of tumor cells and our findings including unchanged expression of IDH1, we speculate that IDH2 plays a crucial role in metabolic reprogramming and biological processes related to GH-PA." (PMID 31455412, 2019). "Beclin-1, ARID1A, CA9 and IDH1 were highly expressed in ICC tumor tissues." (PMID 30849962, 2019). "Furthermore, the mutated IDH1 protein acquires the ability to convert α-ketoglutarate to (R)-2-hydroxyglutarate (2-HG) which could act as an oncometabolite and DJ-1 could exert a potential protective role against oxidative stress in the tumor cells potentially triggered by 2-HG." (PMID 31434323, 2019). "However, there was a significant difference in the overall tumor volume between the two groups: IDH1-mutant patients exhibited larger overall tumor volumes than did IDH1-wild type patients (32.51 ± 10.63 vs 25.11 ± 10.44 cm3)." (PMID 31275753, 2019). "R-2-HG is an oncometabolite and is necessary to maintain tumor phenotype in IDH1 mutant cells." (PMID 30708988, 2019). "The fact that both IDH1-mutant cell lines and recurrent tumor samples showed a similar hypomethylated profile further supports the idea that “passive demethylation” actually plays a role during tumor progression." (PMID 30760837, 2019). "These researchers also found the IDH1 gene in more than 1/5 of the tumor samples." (PMID 31263678, 2019). "The prognostic value of this four-gene IPS was also independent of the known strong prognostic factors, like IDH1 mutation, age, and tumor grade." (PMID 31824866, 2019). "To assay whether Notch3-mediated regulation of Mdh1, Idh1 and Aco1 protein expression really occurs in primary tumours, we examined protein abundance in Notch3-silenced and control rats after brivanib treatment." (PMID 30765875, 2019). "Thus, IDH1-mutant GBM patients featured a larger tumor volume, consistent with the finding in a large cohort study of GBM patients." (PMID 31275753, 2019). "In addition, it was suggested that instead of trying to reduce 2-HG synthesis in patients, consumption of NADPH by the mutant IDH1 can be used as a metabolic weakness to sensitize tumor cells to ionizing radiation." (PMID 31242696, 2019). "Next, we sought to elucidate the effects of IDH1/2 mutations on DNA methylation across six IDH mutant cancer types without wild-type tumor comparisons by identifying common hyper- and hypomethylated probes shared among all IDH1/2 mutant tumor types." (PMID 31727977, 2019). "While none of the cell lines expressed NAPRT, there was a strong expression of NAPRT in the tumor tissues from PDXs, independent of IDH1-mutation status." (PMID 31888244, 2019).
tumor (continued). "Moreover, the associations between the age- and tumor volume-based GBM pathophysiological characteristics of GBM and the pathoetiological mechanisms underlying the IDH1 mutation status need further investigation." (PMID 31275753, 2019). "Forced expression of a mutant IDH1 also suppressed the accumulation of T cells at tumor sites." (PMID 30857299, 2019). "In this example, every one of the tumor samples contains a missense mutation at R132 in IDH1 and no other mutations, while the normal samples do not contain any mutations at this position." (PMID 30700767, 2019). "In wild-type cells it has been shown that FOXOs regulate IDH1 and, as a consequence, cellular differentiation and tumor suppression, probably ensuring adequate NADPH, α-KG and GSH cytoplasmic levels, providing protection against genomic instability and oxidative stress." (PMID 31234353, 2019). "In several studies the IDH1 mutation has proven to be a powerful prognostic factor in diffuse gliomas, irrespective of tumor grade and histology." (PMID 31242696, 2019). "However, the relative increase in IDH1 expression with increasing tumor grade is very modest and expression levels of IDH1 are in general relatively high." (PMID 31240524, 2019). "To investigate what cellular functions may be affected across all six IDH1/2 mutant tumor types, we separately analyzed the effect of hyper- and hypomethylation on promoters, enhancers and gene bodies." (PMID 31727977, 2019). "Primary AML tumor samples were selected based on having known HLA haplotypes for HLA-A, B, C and HLA-DR, and at least one or more common recurrent mutations in either NPM1, FLT3, DNMT3A, IDH1, IDH2, KIT, or RAS from previous clinical evaluation." (PMID 31291378, 2019). "For IDH1/2 mutant tumours, it has been only speculated that D-2-HG production is higher than D-2-HG degradation." (PMID 31092874, 2019). "The authors speculate that the oxidative stress generated by tumor promoters might contribute to IDH1 inactivation." (PMID 31010244, 2019). "Based on the anaplastic features and absence of IDH1 (R132H) mutation, the management consensus after review in a tumor board discussion was concurrent chemoradiotherapy plus adjuvant temozolomide." (PMID 31806041, 2019). "T-cell depletion abrogated the reduction in IDH1-mut tumor growth after IDH1 peptide vaccination." (PMID 30857299, 2019). "Also, the tumor microenvironment contributes to metabolic rewiring in wild-type IDH1/2 tumors, that under hypoxia generate the oncometabolite L-2-HG through a ‘promiscuous’ reduction of α-KG." (PMID 31366176, 2019). "IDH1-mutation status is associated with a localization of the tumor in the frontal lobe, a higher percentage of noncontrast-enhancing part of the tumor, and the presence of cysts on MRI." (PMID 29581794, 2018). "For example, tumors with IDH1/2 mutation accumulate 2-hydroxyglutarate (2-HG) within the tumor, and magnetic resonance spectroscopy (MRS) is thought to be a promising technique to non-invasively detect 2-HG and thus suggest IDH1/2 mutation of the tumor." (PMID 30082856, 2018). "Young age, gross complete tumor resection, neuronavigation with 5 Ala, Gradel (BCNU waffle), irradiation, CCRT, IDH-1 mutation, methylated MGMT, TMZ, Avastin, and immunotherapy have all been studied and may improve the tumor control." (PMID 29910795, 2018). "For now, the data suggest that for patients harboring a tumor with an unfavorable natural history, such as those with intact 1p/19q and wild-type IDH1, TMZ and RT may be the best option." (PMID 30263090, 2018). "In patients harboring a tumor with an unfavorable natural history, such as those with intact 1p/19q and wild-type IDH1, RT/TMZ plus adjuvant TMZ may be the best option." (PMID 30263090, 2018).
tumor (continued). "Moreover, IDH1 was found to be down-regulated in ccRCC tumor tissues, compared with peritumor tissues (p < 0.001)." (PMID 30153799, 2018). "The dying part of tumor tissues may also release IDH1 and IDH2 protein or spread into blood, which may contribute to increasing of serum IDH2 level and a part of the IDH1 and IDH2 detected." (PMID 29465809, 2018). "We, therefore, investigated the expression of IDH1/2 in these tumours and found that expression for both genes was down-regulated in the GBM50 tumours, which likely reduced their ability to induce hyper-methylation and supports the hypo-methylation observed in these tumours." (PMID 30208958, 2018). "Additionally, mutations of FH, SDH, and IDH1/2 cause increased production of reactive oxygen species (ROS), either directly by mutated SDH or indirectly in tumor cells with mutant IDH1/2 and FH." (PMID 28748451, 2018). "We found that HIF2α expression and tumor microvessels formation were independent of the IDH1 mutation status." (PMID 29662659, 2018). "IDH1/IDH2 mutations are associated with the production of an oncogenic metabolite, D-2-hydroxyglutarate (D-2-HG), which appears to be a critical aspect of tumor development." (PMID 30170631, 2018). "It is, therefore, not clear what the overall effect of the IDH1 mutation is on hypoxic tumor phenotype." (PMID 29562167, 2018). "Neither glioblastomas with high and moderate tumor mutational load nor IDH1 mutant gliomas exhibited increased PD-1+ T cell infiltrate or PD-L1 expression by tumor cells in comparison to samples with low tumor mutational load." (PMID 30563098, 2018). "In addition, EGFRvIII and the IDH1 mutant (R132H) represent truly tumour-specific targets that occur within a subset of tumours." (PMID 28412740, 2017). "Apparent loss of 5hmC in tumours can occur through loss-of-function mutations in TET enzymes that oxidise 5mC to 5hmC, or inhibition of TET activity by the oncometabolite beta-hydroxyglutarate generated by mutant IDH1/2." (PMID 29263824, 2017). "Multiple regression analysis revealed that the only tumor volume (P = 0.0294) and mean ADC value (P = 0.0407) based on FLAIR images were significantly correlated with BCAT1 expression level independently with IDH1 mutation status." (PMID 29255149, 2017). "Immunohistochemistry (IHC) detection of IDH1 mutant protein may also be used to visualize single infiltrating tumor cells in surrounding brain tissue with an otherwise normal appearance." (PMID 31548536, 2017). "IDH1 or -2 mutations were found in 60.8% of the central cartilaginous tumours, while mutations in FH and SDH were absent." (PMID 28484589, 2017). "We next assessed whether ABT263 also yields a stronger anti-cancer activity in an IDH1 R132H-expressing isogenic tumor model." (PMID 29057925, 2017). "On the other hand; although several mutations in each of the three IDH3 subunits have been recovered from different types of tumor samples, none of these mutations were found to be as recurrent as IDH1 and 2 activating mutations." (PMID 28785398, 2017). "Moreover, the in vivo tumour promoting effect of fibroblasts depleted of IDH1 was observed in xenografted tumour mice." (PMID 29137396, 2017). "In short, our findings highlight clomifene may have clinical potential in tumor therapies as a safe and effective inhibitor of mutant IDH1." (PMID 28498812, 2017). "However, the time to tumor formation depended on the number of passages for which the cells expressed mutant IDH1." (PMID 28178660, 2017). "Unlike SDH and FH loss-of-function mutations of which have been identified in various cancers, R132 and R172 mutations in IDH1 and 2 (the neomorphic allele producing mutations); respectively, do not follow Knudson’s two-hit model of tumor suppressor genes." (PMID 28785398, 2017).
tumor (continued). "For ten patients, the tumor was 1p19q codeleted but without IDH1 mutation detected by the mIDH1R132 antibody." (PMID 29186201, 2017). "TET2 promoter methylation has previously been observed in low-grade diffuse gliomas lacking IDH1/2 mutations and provides a third mechanism to cause loss in maintenance of 5hmC levels in the tumour." (PMID 29263824, 2017). "Taken together, these data suggest that tumour therapy may contribute to the development of more aggressive IDH1-mutant GBMs by increasing ECM stiffness and reducing miR-203 expression." (PMID 27820599, 2016). "The tumor volume increased after bevacizumab treatment in both IDH1 WT and BCAT1 sh#1 rats." (PMID 27626306, 2016). "Preoperative KPS, IDH1 mutation status, preoperative dT2T1, preoperative contrast enhancement (CE) and tumor location (eloquence, side, lobe) did not impact on tumor resectability." (PMID 27344556, 2016). "This hypothesis is currently supported by a likely successful approach to immunize IDH-1 mutation-positive tumor patients with IDH-1-derived peptides and improved survival of IDH-1-mutated patients." (PMID 27585656, 2016). "Furthermore, we found that IDH1-R132H expression correlated negatively with tumor stage in both GC and CRC." (PMID 27655638, 2016). "Multivariate analysis on IDH1-R132H expression, differentiation, tumor stage, preoperative CA19-9 level, and CEA level revealed that low IDH1-R132H expression (HR, 0.587, P=0.019), tumor stage (HR, 1.533, P<0.001), and preoperative CEA (HR, 2.432, P<0.001) correlated with poor OS." (PMID 27655638, 2016). "Importantly, orthotopically injected R132H IDH1 tumours with reduced miR-203 exhibited decreased survival, increased TNC expression, and elevated ECM stiffness." (PMID 27820599, 2016). "Furthermore, Kaplan–Meier analysis indicated that patients with lower IDH1-R132H expression, lower differentiation, and more advanced tumor stage have a poorer prognosis." (PMID 27655638, 2016). "IDH1 functions as a tumor suppressor since its inactivation contributes to tumorigenesis." (PMID 27655638, 2016). "Besides, IDH1-R132H expression was also related with tumor stage (X2=13.1516, P=0.004), lymph node metastasis (X2=9.6676, P=0.022) and distant metastasis (X2=7.4030, P=0.007)." (PMID 27655638, 2016). "Importantly, survival was decreased in mice bearing orthotopic R132H IDH1 GBM tumours expressing the constitutively active HIF1α (CA-HIF) compared with vector-only tumours." (PMID 27820599, 2016). "Accordingly, we asked whether the post-treatment (secondary) IDH1-mutant GBMs were stiffer than the patient-matched primary LGG or GBM tumours." (PMID 27820599, 2016). "Fifteen of the 86 tumor samples showed immunoreactivity for mutant R132H IDH1 protein (mIDH1R132)." (PMID 27626492, 2016). "We found high sensitivity for IDH1-R132H even in small amounts of tumor tissue." (PMID 27877908, 2016). "All samples were primary tumours, fresh frozen and IDH1 and IDH2 wild type." (PMID 27886174, 2016). "However, after ROC analysis, neither Ki67 (AUC = 0.688; p = NS) nor mitotic index (AUC = 0.569; p = NS) demonstrated significant predictive power for the IDH1-R132H status of the tumour." (PMID 25849605, 2015).
tumor (continued). "This may have therapeutic consequences in SBA as recently it has been shown that mutant IDH1 can be targeted with anti-tumor vaccines." (PMID 26315110, 2015). "An increased risk of death was associated with contrast-enhancement ≥ 5 cm3 in patients with IDH1-R132H-positive tumours while edema ≥ 1 cm beyond the tumour margin and < 5 mitoses/mm2 were associated with an increased risk of death in patients with IDH1-R132H-negative tumours." (PMID 25849605, 2015). "Mutations in the Sdh genes as well as gain-on-function mutations in the Idh1 or Idh2 genes should be excluded in this case, due to the absence of clonality in the non-tumor liver tissue, in contrast to tumors." (PMID 25918251, 2015). "Another novel finding of the present study is that IDH1-R132H positive tumours have a higher minimum ADC (optimal cut-point ≥ 0.950 x 10-3 mm2/sec) when compared to IDH1-R132H negative tumours although this feature only had moderate power for predicting the status of the tumour." (PMID 25849605, 2015). "Finally, p16/CDKN2A copy number variation is seen in both the IDH1 wild-type and mutant cartilaginous central tumours." (PMID 25432631, 2015). "The Ki-67 index was significantly lower in IDH1-R132H-positive tumours (0.13 vs. 0.21; p=0.034)." (PMID 25849605, 2015). "A ROC analysis was performed to determine if any of the MRI features assessed could be used to predict the IDH1-R132H status of the tumour." (PMID 25849605, 2015). "Second, we found that in patients with IDH1-R132H negative tumours, edema extending more than 1 cm beyond the margin of the tumour was associated with a higher rate of death at 12 months." (PMID 25849605, 2015). "Ten out of 18 IDH1-R132H positive tumours (55%) were located in the frontal lobe." (PMID 25849605, 2015). "Of the 8 sample sets from the 31 patients which revealed discordant p16/CDKN2A copy number, loss of p16/CDKN2A was observed in the relapse event and not in the primary tumour in 5 cases (3 of which also harboured IDH1 mutation)." (PMID 25432631, 2015). "Intriguingly, one tumour was co-mutated for IDH1 (R132H) and IDH2 (P162S), but exhibited no distinguishing phenotype in terms of clinicopathology or mutation rate." (PMID 26068201, 2015). "For example, a 55-year-old patient with a KPS of 80 and a partly resected/IDH1 wild-type/MGMT-methylated tumor has a total prognostic score of 129 and is predicted to have a median survival of approximately 30 months and a 60% probability of surviving two years." (PMID 25233099, 2014). "Mutations in PIK3CA, PTEN, AKT1, IDH1 and IDH2 have been reported in this class of tumours." (PMID 24867389, 2014). "Similarly, there was an association between IDH1 mutations, PTEN status and tumour grade; a higher proportion of AA/AOA tumours (36/41, 75%) were PTEN normal vs 52/211 (25%) GBs." (PMID 24952577, 2014). "In addition, microvesicles can accurately model the profile of the tumor cell including changes in IDH-1, EGFR, and EGFRvIII." (PMID 25312641, 2014). "There was an association between IDH1 mutations and MGMT methylation (higher IDH1 mutation rates in methylated tumours) across all tumour grades; this was statistically significant (Fisher’s exact test, p <0.01) for both AOA/AA and GB patients, but was most marked in the AOAs and AAs." (PMID 24952577, 2014). "Among the 84 tumor samples with low ATRX mRNA expression, 44 had mutations in either IDH1 or IDH2, while 34 were WT for both genes, indicating a strong association between ATRX mRNA expression and IDH1/2 mutations (P<0.0001, Chi-Square test)." (PMID 24810474, 2014). "Tumours negative for IDH1 mutations frequently exhibited mutations at the analogous amino acid (R172) of the IDH2." (PMID 23998913, 2013). "Interestingly, IDH1-mutant tumor cells in vivo present with high densities of mitochondria and increased levels of mitochondrial activity as compared to IDH1-wildtype xenografts." (PMID 24252742, 2013).